SAMHD1 (SAM and HD domain containing deoxynucleoside triphosphate triphosphohydrolase 1)
Diseases named in the same sentence as SAMHD1 in open-access papers (continued):
Sharing a sentence is not in itself a finding about the gene and the disease.
infection (continued). "In contrast, non-opsonized HIV-1 only causes low-level productive infection of DCs due to SAMHD1 restriction and this low-level infection is associated with low-level antiviral actions and CTL induction, thus viral evasion." (PMID 33224139, 2020). "Interestingly, pretreatment of MDMGs with SIVmac Vpx VLPs significantly enhanced p24Gag production, suggesting that abundant expression of antiviral SAMHD1 in MDMGs restricts efficient infection of these cells by HIV-1." (PMID 33298546, 2020). "We observed a similar loss of SAMHD1 and a similar effect of MLN4924 during infection of Toledo and JHC strains, suggesting that this SAMHD1 regulation is well-conserved among HCMV strains, and that the UL/b′ region, which is absent in the Towne strain, is not required for this regulation." (PMID 32850489, 2020). "We therefore considered the possibility that SAMHD1 may also restrict infection in tissue-derived CD4+ T cells." (PMID 32353080, 2020). "However, a much larger fraction of cores were stable in the cytoplasm of MDMs compared with TZM-bl cells, even after depletion of SAMHD1 in MDMs which facilitates vDNA synthesis and infection by raising the intracellular dNTP levels." (PMID 33143125, 2020). "Our findings, however, suggest that SAMHD1 restriction is unlikely the mechanism preventing productive infection of CD127+ Tm cells, since active SAMHD1 was expressed at similar levels in CD127+ Tm cells and the highly susceptible CD57+ and CD57-CD127- Tm subsets." (PMID 32353080, 2020). "This cell-to-cell infection process bypasses the restriction imposed by the SAMHD1 host cell restriction factor for HIV-1 replication, leading to the formation of highly virus-productive multinucleated giant cells as observed in vivo in lymphoid and nonlymphoid tissues of HIV-1-infected patients." (PMID 31744918, 2019). "We show that the expression of the interferon-stimulated proteins MX1, IFIT1, IFIT3 and ISG15, as well as expression of defense response proteins DDX58, STAT1, OAS3, EIF2AK2 and SAMHD1 was significantly up-regulated in these cells upon infection with either virus." (PMID 30959732, 2019). "By contrast, it did not restrict HIV‐2 and SIVsm infections because they encode the SAMHD1 antagonist protein Vpx." (PMID 29084722, 2018). "To determine whether the lower amount of phosphorylated SAMHD1 was responsible for the block to infection induced by NCS, we tested whether Vpx, which degrades SAMHD1, would alleviate the inhibition of infection using HIV-1 virions containing Vpx." (PMID 29515139, 2018). "However, despite similarities between the proteins, HIV-1 Vpr appears unable to substitute for SIV Vpx in enhancing macrophage infection in the presence of SAMHD1." (PMID 30656243, 2018). "The block to infection was at early reverse transcription and was overcome by packaging Vpx into the virions, demonstrating that the block was caused by SAMHD1 and not by other cellular alterations induced by DNA damage." (PMID 29515139, 2018). "However, because SAMHD1 knock-down creates permissive conditions for SIVΔvpx infection, it appears that SAMHD1 is the key factor blocking SIVΔvpx infection as well as the main target for Vpx." (PMID 30656243, 2018). "Notably, the points of infection were specifically chosen to ensure that onset of RT coincided with different cell cycle-phases and SAMHD1 phosphorylation states." (PMID 29884836, 2018). "It was hypothesized that HIV-1 lacks a countermeasure against SAMHD1 because it is beneficial for infection." (PMID 29176984, 2017). "Early work suggested that enhanced infection by SAMHD1 depletion leads to DC maturation." (PMID 29176984, 2017). "Both MX1 and SAMHD1 expression were positively correlated with severity of CNS disease, consistent with a runaway immune response that, in acute phase infection, might be protective, but at later stages becomes damaging." (PMID 26936683, 2016).
infection (continued). "Furthermore, for the first time, we used an infection model based on SAMHD1 silenced HepG2-NTCP cells to prove the relevance of endogenous SAMHD1 restriction on HBV infection." (PMID 27229711, 2016). "Additional mechanisms by which SAMHD1 might restrict infection have been proposed and include degradation and/or binding of viral nucleic acids (Ballana and Esté, 2015)." (PMID 27477283, 2016). "To determine whether R848 inhibition was dependent on SAMHD1, we tested whether the drug blocked the infection of SAMHD1 knock-out mouse bone marrow derived DCs (BMDC)." (PMID 27905985, 2016). "This raised the possibility that SFN triggers SAMHD1 production in U937 cells to block infection." (PMID 27093399, 2016). "Interestingly, in the HepG2-NTCP infection model, SAMHD1 knockdown increases the level of intracellular viral DNA compared to the control, without significantly affecting the level of cccDNA." (PMID 27229711, 2016). "To test whether the R848-induced block to infection was mediated by SAMHD1, we treated monocytes with the drug for 24 h and then infected them with Vpx-containing HIV-1 or control supernatant." (PMID 27905985, 2016). "Our results indicate that SAMHD1 mRNA expression in thalamus mirrors the rise of proinflammatory cytokine expression during acute infection and appears to remain elevated during asymptomatic infection and into disease progression." (PMID 26936683, 2016). "Together, these results demonstrate that SIV Vpx mutants bearing the Q76A point mutation, which specifically blocks the recruitment of DCAF1, are defective in degrading endogenous SAMHD1 and are attenuated during spreading infections in cultured activated PBMC compared to their WT counterparts." (PMID 25996507, 2015). "Given that SAMHD1, an intrinsic dNTP triphosphohydrolase, depletes cellular dNTP levels (which are required by reverse transcriptase for efficient synthesis of retroviral cDNA), it was believed that SAMHD1 would also inhibit infection by retroviruses other than HIV-1." (PMID 26032178, 2015). "In addition, SAMHD1 is an anti-HIV-1 restriction factor that blocks the infection of monocyte-derived dendritic cells (MDDCs), monocyte-derived macrophages (MDMs), and resting T cells through its triphosphohydrolase activity." (PMID 25331707, 2015). "SAMHD1 is a restriction factor that blocks infection of certain immune cells by HIV-1." (PMID 26431200, 2015). "Therefore, we here showed that complement-opsonization of HIV-1 significantly enhances DC infection and SAMHD1 phosphorylation independent on the use of single-cycle or replicating virus." (PMID 26121641, 2015). "However, although the removal of the SAMHD1 block renders the cells more permissive to infection, the removal also results in greater immune responses." (PMID 25331707, 2015). "By examining vDNA accumulated in conditions that are well known to modulate the restriction specified by SAMHD1, we have been able to gather an interesting correlation between the efficiency of the infection process in DCs and the frequency of cytidine deamination of vDNA." (PMID 26496699, 2015). "We next determined whether the capacity of the putative revertant viruses to degrade endogenous SAMHD1 was restored during productive in vitro infections." (PMID 25996507, 2015). "Therefore, by slowing down the reverse transcription process, SAMHD1 may indirectly modulate the susceptibility of vDNA to A3-editing, thus explaining the inverse correlation observed here between editing on one hand and success of infection and speed of reverse transcription on the other." (PMID 26496699, 2015). "In short-term in vivo infection experiments using two different mouse gamma-retroviruses, Friend virus and M-MLV, virus replication and virus-induced pathology were comparable in wild-type and SAMHD1-deficient mice." (PMID 24854580, 2014).
infection (continued). "Supporting the notion that SAMHD1's influence on infection may be more complex, it has been suggested that SAMHD1 interacts with nucleic acids, specifically ssRNA and ssDNA and that it possesses a nuclease activity." (PMID 24782834, 2014). "Importantly, depletion of SAMHD1 in myeloid cells by RNA interference at least partly phenocopies the effect of Vpx and facilitates infection with HIV-1-derived lentivectors." (PMID 24854580, 2014). "Accordingly, increased levels of NL43-Luci/VSV-G infection were observed in monocytes and GM-CSF-differentiated macrophages transfected with the siRNAs targeting SAMHD1." (PMID 24599229, 2014). "Surprisingly, rescue could be achieved even 24 h post-infection, arguing against the recently suggested nuclease activity for SAMHD1 acting on incoming viral RNA." (PMID 24656066, 2014). "Moreover, SAMHD1 facilitates apoptosis in monocytes that is induced by infection with the delta-retrovirus human T cell leukaemia virus type 1." (PMID 24854580, 2014). "Since then rapid progress has been made in characterising in detail how SAMHD1 controls infection." (PMID 24854580, 2014). "The recently discovered restriction factor SAMHD1 blocks infection of HIV-1 and other retroviruses." (PMID 24219908, 2013). "In addition to HIV-1, SAMHD1 also blocks infection of other retroviruses, including HIV-2, feline immunodeficiency virus, bovine immunodeficiency virus, equine infectious anemia virus, and murine leukemia viruses." (PMID 24523981, 2013). "Similarly to PMA-differentiated THP-1 cells, the addition of Vpx+ VLPs caused a decrease in SAMHD1 protein levels, and enhanced HSV-1 KOS infection by 10.4-fold as compared to primary DCs treated with Vpx− VLPs." (PMID 23825958, 2013). "SAMHD1 is a restriction factor that potently blocks infection by HIV-1 and other retroviruses." (PMID 24219908, 2013). "The only two vpx alleles that were inactive in antagonizing SAMHD1 and failed to boost myeloid cell infection were both derived from individual RH2-3, who efficiently controlled viral replication." (PMID 23497283, 2013). "Collectively, data from experiments using WR and WRΔTK viruses suggest that Vpx-mediated SAMHD1 degradation enhances vaccinia virus infection in MDMs, with an even greater enhancement of infection in the absence of the viral encoded TK gene." (PMID 23825958, 2013). "Thus, all HIV-2 Vpx proteins that degraded SAMHD1 in transfection assays were also capable of promoting macrophage infection." (PMID 23497283, 2013). "Two vpx alleles (RH2-3 8A3 and 2C5) had little if any effect on SAMHD1 expression levels and failed to promote macrophage infection." (PMID 23497283, 2013). "Rather SAMHD1 and the interferon pathway likely act in synergy to prevent the infection." (PMID 23497353, 2013). "While it is likely that the effect of Vpx is not specifically on reverse transcription, the Vpx-induced degradation of SAMHD1 results in a larger intracellular dNTP pool which allows reverse transcription to proceed and restores permissiveness of the cells to infection." (PMID 22913641, 2012). "We recently reported that common polymorphisms of SAMHD1 are unlikely to contribute to the infection and natural control of HIV-1, at least in European and African-American individuals." (PMID 23231760, 2012). "It would be intriguing to examine whether SAMHD1 knockout mice mirror the AGS symptoms in human patients and become more susceptible to the infection with murine retroviruses or other RNA or DNA viruses." (PMID 23092163, 2012). "Consistent with our expectations, treatment with baricitinib did not alter the susceptibility of Samhd1-deficient larvae to STM infection, which showed a survival rate approximately 30% higher than that of WT larvae and similar to that of untreated Samhd1-deficient larvae." (PMID 40352920, 2025). "Interestingly, the mRNA levels of tnfα and ifng1r from the Samhd1-deficient infected larvae did not overcome those of the control post-infection." (PMID 40352920, 2025).
infection (continued). "SAMHD1 loss generally correlated with the high level expression of viral late proteins, such as the SUMO-modified form of viral immediate-early (IE) 2 (IE2-SUMO) and UL99-encoded pp28, indicating that the overall reduction of SAMHD1 level is evident at late stages of infection." (PMID 32850489, 2020). "Infection of ovine cells by SeV could counteract this activity by reducing SAMHD1 expression." (PMID 32365702, 2020). "We found that treatment of MG132 or MLN4924 at 72 h after infection partly inhibited SAMHD1 loss at 96 h as above, however, bafilomycin A1 did not inhibit SAMHD1 loss at all, suggesting that the virus-induced SAMHD1 loss occurs through the non-lysosomal pathways." (PMID 32850489, 2020). "The low levels of infection observed in myeloid cells, even in the presence of Vpx, could be explained by an inability of Vpx to overcome SAMHD1 completely, other post-entry restriction factors, or by CD4 and/or coreceptor densities that are too low to facilitate efficient entry." (PMID 32992787, 2020). "Thus, there appears to be a strict interplay between cellular and viral kinases in SAMHD1 phosphorylation, that could be differently regulated depending on the time post-infection." (PMID 32986788, 2020). "However, Vpx also increased the overall pathogenesis of infections, making it difficult to ascertain whether elevated rates of macrophage infection were mediated by Vpx degradation of SAMHD1 or overall disease pathogenesis." (PMID 32992787, 2020). "Although this suggests that HCMV might have evolved several strategies to finely regulate SAMHD1 level during productive infection, the underlying mechanisms have not been studied." (PMID 32850489, 2020). "Furthermore, higher infection observed with SAMHD1 depletion correlates with a stronger suppression of maturation, suggesting that HIV-1 might actively suppress PRR sensing." (PMID 31354736, 2019). "Interestingly, the functionally active, de-phosphorylated form of SAMHD1 is preferentially found in primary DCs isolated ex vivo from human blood, which potentially could contribute to a higher resistance to infection." (PMID 31244850, 2019). "In order to characterize the effect of Vpx-mediated SAMHD1 degradation on the dynamics of reverse transcription in more detail, we quantitated different RT products in samples from inhibitor time-of-addition experiments by ddPCR, including early time points post infection." (PMID 30423802, 2018). "In addition, the R848-induced block to infection of monocytes was not relieved by Vpx, which causes the rapid degradation of SAMHD1." (PMID 27905985, 2016). "It is presently unclear whether compromised infection of myeloid lineage cells in vivo is responsible for this phenotype or if endogenous SAMHD1 must also be suppressed in memory CD4+ T lymphocytes, the cell lineage that sustains high levels of set-point viremia attending pathogenic infection." (PMID 25996507, 2015). "Consistently, only RNase activity-possessing SAMHD1 variants effectively blocked the production of F-MLV late reverse transcripts, whereas RNase-defective SAMHD1 mutants led to a robust increase in the amount of viral reverse transcripts at 24 h post-infection." (PMID 26032178, 2015). "Alternatively, SAMHD1's ability to restrict infection may be down regulated in some cells." (PMID 24465411, 2014). "To verify that the enhanced infection of SAMHD1Δ/Δ BMDCs was due to the absence of SAMHD1 activity, we complemented SAMHD1Δ/Δ cells by transduction with lentiviral particles encoding murine SAMHD1 or empty vector prior to infection with NL43-CMVGFP." (PMID 23972988, 2013). "Furthermore, we observed that Vpx-mediated SAMHD1 degradation increased infection of DCs with R5-tropic, replication-competent HIV-1NLAD8, as evidenced by 4-fold enhancement of p24 production in the supernatants from infected DCs at 72 hr post-infection (p <0.001)." (PMID 23231760, 2012).
infection (continued). "In agreement, localization studies of the Vpx protein during lentiviral infection correlated the nuclear localization of Vpx with its ability to promote productive infection in primary macrophages, which suggests that Vpx might overcome the viral-block imposed by SAMHD1 in the nucleus." (PMID 22691373, 2012). "The percentages of total apoptosis in THP-1 Ctrl and SAMHD1 KI cells, which expressed similar levels of SAMHD1 protein, were higher than that observed in SAMHD1 KO and Lvx cells upon HIV-1-Luc/VSV-G infection." (PMID 40434097, 2025). "To investigate how USP37 affects the function of SAMHD1, we knocked down or overexpressed USP37 in THP-1 cells, the target cells for SIV infection, and examined its impact on the infection of SIVmac239 WT or SIVmac239 ΔVpx." (PMID 39655951, 2025). "Compared to SAMHD1 KO cells, HIV-1NL4-3 infection in THP-1 Ctrl cells induced higher cleavage of caspases 3/7 and PARP at 4 and 6 dpi." (PMID 40434097, 2025). "Therefore, unlike authentic SARS-CoV-2, SAMHD1 deficiency did not inhibit ΔS-VRP(G) infection." (PMID 41280104, 2025). "Suppression of IFN signaling of SAMHD1-defective HEK293T cells by baricitinib, a JAK1/2 inhibitor, alleviated the repression of SARS-CoV-2 replication, suggesting that SARS-CoV-2 exploits SAMHD1 for IFN antagonism, thereby facilitating its infection." (PMID 41280104, 2025). "At 2, 3, and 4 dpi, HIV-1-Luc/VSV-G infection significantly decreased Δψm of THP-1 Ctrl cells, while the reduction in SAMHD1 KO cells was milder compared with that in THP-1 Ctrl cells." (PMID 40434097, 2025). "The shRNA-mediated depletion of GJB2 enhanced the spread of HIV-1 over the 18 day infection period in MDDCs, which became more permissible to the virus following pretreatment with virus-like particle (VLP)-Vpx to deplete SAMHD1 protein." (PMID 40980890, 2025). "THP-1 Ctrl and SAMHD1 KI cells exhibited enhanced cleavage of caspases 3/7 and PARP compared to SAMHD1 KO and Lvx cells upon HIV-1-Luc/VSV-G infection." (PMID 40434097, 2025). "By examining the changes of SAMHD1 after H5N1 and H1N1 different MOI infection, we found that the down-regulation effect of IAV on SAMHD1 is broad spectrum." (PMID 38287375, 2024). "The high p24 detected in their CD11c+ AXL+ DCs was due to infection by HIV-1 (NL-AD8) in the presence of Vpx, thus neutralising SAMHD1." (PMID 38924030, 2024). "TVs expressing sgRNAs targeting known RFs like TRIM5, IFI16, IFITM2, SAMHD1, GBP5 and IFITM1 were enriched after 15 and 20 days post-infection confirming that targeting RFs provides a selection advantage to the respective viruses." (PMID 38714682, 2024). "It is interesting that Vpx’s antagonism of APOBEC3A to both enhance myeloid cell infection and possibly HIV gene expression is mirrored in its antagonism of SAMHD1 and HuSH, respectively." (PMID 39205287, 2024). "HIV-1-mCherry infection, as measured by %mCherry+ cells in CD11b+ viable GFP+ transdifferentiated BLaER1 cells, was strongly increased upon SAMHD1 KO at 24 hpi (Clone #1 P = 0.3633, #2 P = 0.0360, #3 P = 0.0013, n = 5, Kruskal–Wallis test)." (PMID 37800914, 2023). "When compared to SAMHD1 KO, HIV-1-mCherry infection at MOI1 was significantly lower in D218A (P < 0.0001, n = 3, one-way ANOVA), but similar in D210A and D311A mutants." (PMID 37800914, 2023). "Infection of primary monocytes with HTLV-1 leads to SAMHD1-mediated apoptosis, and SAMHD1 also blocks HTLV-1 infection through RTI-stimulated STING-IRF3-BAX-driven apoptosis." (PMID 37242405, 2023). "For example, during spreading infection in Jurkat T cells, which lack active SAMHD1 and cGAS, WT SIVmac and ∆vpx viruses replicate similarly, unless STING is activated with agonist (RR-S2 CDA), and then Vpx enhances infection, consistent with our data." (PMID 35073912, 2022). "Two weeks after nucleofection, reduced levels of SAMHD1 in SAMHD1 KO cells enhanced HIV-1* GFP infection significantly, by 2.5-fold, compared to NTC reference cells (top)." (PMID 34949807, 2022).